TMC8 (transmembrane channel like 8)
Description:
Acts as a regulatory protein involved in the regulation of numerous cellular processes. Together with its homolog TMC6/EVER1, forms a complex with calcium-binding protein CIB1 in lymphocytes and keratynocytes where TMC6 and TMC8 stabilize CIB1 levels and reciprocally. Together with TMC6, also forms a complex with and activates zinc transporter ZNT1 at the ER membrane of keratynocytes, thereby facilitating zinc uptake into the ER. Also inhibits receptor-mediated calcium release from ER stores and calcium activated and volume regulated chloride channels. Down-regulates the activity of transcription factors induced by zinc and cytokines. Also sequesters TRADD which impairs the recruitment of TRAF2 and RIPK1 in the pro-survival complex I and promotes proapoptotic complex II formation, and may therefore be involved in TNF-induced cell death/survival decisions.
Synonyms: EVER2; EVIN2; EV2
Tractability: Antibody: UniProt predicts a signal peptide or a membrane-spanning region; its Gene Ontology location is reachable by antibodies, with medium confidence. PROTAC: ubiquitination databases record sites on it; its protein half-life has been measured.
Gene: Protein-coding gene on chromosome 17 (78,130,770 to 78,142,968, forward strand). Ensembl gene ENSG00000167895.
Subcellular location: Endoplasmic reticulum membrane; Golgi apparatus membrane; Nucleus membrane
Subcellular location (Human Protein Atlas): Golgi apparatus
Gene Ontology:
Molecular function: protein binding; protein sequestering activity; tumor necrosis factor binding; mechanosensitive monoatomic ion channel activity
Biological process: intracellular zinc ion homeostasis; negative regulation of canonical NF-kappaB signal transduction; negative regulation of protein binding; negative regulation of protein-containing complex assembly; positive regulation of apoptotic process; protein stabilization; regulation of extrinsic apoptotic signaling pathway via death domain receptors; regulation of tumor necrosis factor-mediated signaling pathway; monoatomic ion transmembrane transport
Cellular component: cytoplasm; endoplasmic reticulum; endoplasmic reticulum membrane; extracellular exosome; extracellular region; Golgi apparatus; Golgi membrane; nuclear membrane; plasma membrane; membrane
Genetic constraint (gnomAD): Loss-of-function variants: 72 observed, 72.93 expected, observed/expected ratio (o/e) 0.99, 90% interval 0.81 to 1.2. The upper end of that interval is the gene's LOEUF score, 1.2, which puts it in group 5 of 6, group 1 being the genes least tolerant of losing a copy. Missense variants: 924 observed, 925.62 expected, observed/expected ratio (o/e) 1, 90% interval 0.94 to 1.05. Synonymous variants: 433 observed, 424.17 expected, observed/expected ratio (o/e) 1.02, 90% interval 0.94 to 1.11.
Homologues: Orthologues: chimpanzee TMC8 (98% identical), macaque TMC8 (96% identical), dog TMC8 (79% identical), mouse Tmc8 (78% identical), pig TMC8 (78% identical), rat Tmc8 (76% identical), guinea pig TMC8 (74% identical), tropical clawed frog tmc8 (33% identical), zebrafish tmc8 (27% identical), Caenorhabditis elegans tmc-2 (21% identical), Caenorhabditis elegans tmc-1 (21% identical). Paralogues in human: TMC4 (31% identical), TMC7 (30% identical), TMC3 (22% identical), TMC6 (22% identical), TMC5 (21% identical), TMC2 (21% identical), TMC1 (19% identical).
Diseases named in the same sentence as TMC8 in open-access papers:
TMC8 is named in the same sentence as 32 diseases in open-access papers, as found by Europe PMC text mining. Sharing a sentence is not in itself a finding about the gene and the disease. The quoted sentences say what the papers report.
epidermodysplasia verruciformis (17 papers, 2010 to 2025). A rare inherited genodermatosis characterized by chronic infection with human papillomavirus (HPV) leading to polymorphous cutaneous lesions and high risk of developing non melanoma skin cancer. "TMC6 and TMC8 have been reported to contribute to epidermodysplasia verruciformis, and predisposition to HPV." (PMID 38440182, 2024). "As for the other TMC molecules, mutations in TMC6 (EVER1) and TMC8 (EVER2) are implicated in epidermodysplasia verruciformis." (PMID 34429071, 2021). "Mutations in TMC8 are associated with Epidermodysplasia verruciformis." (PMID 38746380, 2024). "Mutations in the EVER1 (TMC6) and EVER2 (TMC8) genes are clinically associated with autosomal recessive epidermodysplasia verruciformis (AR-EV)." (PMID 40534698, 2025). "In this case, transcriptome sequencing identified two heterozygous variants in genes classically associated with epidermodysplasia verruciformis: TMC6 (EVER1) and TMC8 (EVER2)." (PMID 40534698, 2025). "This association was first described in patients with epidermodysplasia verruciformis, a skin disease caused by an autosomal recessive disorder in the TMC6 (EVER1) and TMC8 (EVER2) genes." (PMID 37877723, 2023). "In the case of patients suffering from the rare hereditary disease Epidermodysplasia verruciformis (EV), mutations within at least two genes of homologous transmembrane channel-like (TMC) proteins, TMC6 (EVER1) and TMC8 (EVER2) were described." (PMID 29770129, 2018). "Epidermodysplasia verruciformis (EV) is a rare genetic dermatological disorder inherited in an autosomal recessive manner, primarily associated with inactivating mutations in the TMC6 (EVER1) and TMC8 (EVER2) genes." (PMID 40666071, 2025). "Patients with epidermodysplasia verruciformis (EV) are particularly susceptible to HPV infection, particularly beta-HPV genotypes, due to autosomal recessive mutations in the TMC6 (EVER1) and TMC8 (EVER2) genes." (PMID 40227794, 2025). "Epidermodysplasia verruciformis (EV) is typically inherited in an autosomal recessive manner, with cases linked to mutations in the EVER1/TMC6 and EVER2/TMC8 genes." (PMID 40534698, 2025).
cervical cancer (4 papers, 2012 to 2023). A primary or metastatic malignant neoplasm involving the cervix. "The EVER 1 and EVER2 genes (also referred to as TMC6 and TMC8 genes), located on the chromosome 17q25 are two of the genetic polymorphisms which were recently related to cervical cancer." (PMID 27899077, 2016). "In recent years, evidence has indicated that TMC6 (also known as EVER1) and TMC8 (also known as EVER2) play a role in cervical cancer and squamous cell carcinoma." (PMID 34899684, 2021). "That effort identified 8 potential genes associated with cervical cancer, including the immune genes 2′,5′ oligoadenylate synthetase gene 3 (OAS3) and sulfatase 1 (SULF1), and the epidermal dysplasia verruciformis (EV)-associated EVER1 and EVER2 genes, TMC6 and TMC8." (PMID 22496757, 2012).
viral infection (3 papers, 2010 to 2025). "Typical EV patients exhibit normal control of most viral infections; Tmc6-/-, Tmc8-/- and wildtype FVB mice similarly controlled vaccinia virus after skin challenge and induced neutralizing antibodies." (PMID 39813296, 2025). "Other viral infections, such as vaccinia, whose control also involves humoral immunity could still be cleared by Tmc6-/- or Tmc8-/- hosts given their normal humoral and partially functional cellular immune systems, as seen in classic EV patients." (PMID 39813296, 2025).
immune deficiency (2 papers, 2025). "Importantly, no mutations were detected in other known EV-associated or immunodeficiency-related genes, such as RHOH, IL7, CORO1A, STK4, DOCK8, or CARMIL2, supporting the notion that the identified TMC6 and TMC8 variants may represent the primary genetic contributors in this case." (PMID 40534698, 2025).
Obesity (2 papers, 2018 to 2023). Accumulation of substantial excess body fat. "Rare variants in the TMC8 gene, which encodes for a transmembrane channel-like protein, were previously discovered to be associated with type 2 diabetes (T2D) and obesity in Russian and Japanese patient cohorts." (PMID 36788222, 2023). "In our study, we observed several highly case-specific variants in genes previously not directly linked to T2D and/or obesity (e.g., TMC8, PCDHA1, PLEKHA5, HBQ1, VAV3, and ADAMTS13)." (PMID 30126146, 2018).
Primary immunodeficiency (2 papers, 2016 to 2024). "We report a novel primary immunodeficiency, and a differential molecular diagnosis to CXCR4‐,DOCK8‐,GATA2‐,MAGT1‐,MCM4‐,STK4‐,RHOH‐,TMC6‐, and TMC8‐related diseases." (PMID 27896283, 2016).
lung carcinoma (1 paper, 2024). "These genes include GRIA3, TAF7L, ARL14, PCDHGA9, MDGA1, ZFPM2, OSR2, TMC8/TMC6, HCN2, and CDK5R2, which are likely to be relevant in human lung cancer and are also epigenetically deregulated upon exposure to ECS in our animal study." (PMID 39273313, 2024).
myeloma (1 paper, 2025). "Currently, very little is known about the transcriptional regulation of TMC6 and TMC8: their expression is high in T-cells and DNA sensing pathways activate their expression in the immortalized NIKS keratinocyte and the myeloma-derived RPMI-8226T cell lines." (PMID 41135646, 2025).
prostate carcinoma (1 paper, 2022). A carcinoma that arises from epithelial cells of the prostate gland. "Mutations in TMC6 (EVER1) and TMC8 (EVER2) may be involved in epidermodysplasia of the pancreas, also known as Tree Man syndrome, and increased expression of Tmc5 may be involved in the proliferation of prostate cancer." (PMID 36451105, 2022).
skin melanoma (1 paper, 2021). "Multivariate analyses based on TMC8 expression (median as the cut-off to divide the patients into high- or low-group) and patient clinical characteristics in the four cohorts showed that TMC8 expression was an independent prognostic biomarker for overall survival in skin melanoma." (PMID 34899684, 2021).
visual disorders (1 paper, 2016). "Eight positively selected genes within the tarsier lineage were implicated in several diseases associated with eye development and visual disorders (BBS2, BFSP2, IDUA, IL1A, IMPG1, RGR, SRD5A3 and TMC8)." (PMID 27708261, 2016).
cancer (7 papers, 2010 to 2024). A tumor composed of atypical neoplastic, often pleomorphic cells that invade other tissues. "Further, TMC4, TMC5, TMC6, TMC7, and TMC8 were tissue-specifically and cancer-specifically expressed." (PMID 34899684, 2021). "We also report an association between genes in EVER1/TMC6 and EVER2/TMC8 and a SNP that lies between the two genes with progression to CIN3/cancer." (PMID 20084279, 2010). "Further, expression of TMC8 was significantly upregulated in patients with cancers that were HPV-positive compared to HPV-negative implying its significance in defense against HPV-derived cancers." (PMID 39077751, 2024). "However, dysregulation of TMC8 could affect cancer progression, suggesting that this protein regulates the cell cycle in infinitely proliferative cells like PSCs." (PMID 39765710, 2024). "The relationship between the function of TMC8 and human cancers has not been studied." (PMID 39765710, 2024).
tumor (4 papers, 2019 to 2023). "Therefore, we further confirmed whether the upregulated BAMBI, SLC26A9, SGPP2, and TMC8 genes could be used as a gene signature for EBVaCAs by determining the expression levels of these four genes in cell lines and tumor tissues by qRT-PCR." (PMID 35008199, 2021). "The HPA database showed that proteins (CD177, LGALS2, TMC8, and VWA5A) were significantly dysregulated in tumor tissue relative to normal samples." (PMID 37528394, 2023). "Based on the changes in the expression levels of genes in EBV-infected cell lines and tumor tissues, we identified two upregulated genes, SLC26A9 and TMC8, as gene signatures for EBVaCAs." (PMID 35008199, 2021). "Two genes, SLC26A9 and TMC8, were identified as gene signatures for EBVaCAs because these two genes were upregulated in all EBV-positive cell lines and tumor tissues." (PMID 35008199, 2021). "We also used data from Human Protein Profiles to demonstrate that the proteins encoded by seven immune-related genes were expressed at different degrees in HCC tissues, among which TMC8, BIN2, GIMAP7, and SPOCK2 were strongly to moderately positive in tumours." (PMID 32213661, 2020). "The results showed that elevated expression of TMC8 and BIN2 relative mRNA in tumor tissues compared to adjacent normal tissues." (PMID 32213661, 2020). "Furthermore, TMC8, BIN2 and SPOCK2 protein levels were also consistently higher expressed in tumor tissues than those in normal liver tissues." (PMID 32213661, 2020). "However, SLC26A9 and TMC8, but not BAMBI and SGPP2, were significantly upregulated in EBV-positive tumor tissues compared to EBV-negative tumor tissues." (PMID 35008199, 2021). "Similarly, the expression of SLC26A9 and TMC8, but not BAMBI or SGPP2, was significantly upregulated in EBV-positive tumor tissues compared with that in EBV-negative tumor tissues." (PMID 35008199, 2021).
genodermatosis (3 papers, 2012 to 2024). "Congenital epidermodysplasia verruciformis (CEV) is a Genodermatosis linked to different inheritance patterns and mutations of the EVER1/TMC6 and EVER2/TMC8 genes." (PMID 39001899, 2024).
infection (2 papers, 2010 to 2025). The state of being infected such as from the introduction of a foreign agent such as serum, vaccine, antigenic substance or organism. "This suggests that Tmc6 and Tmc8 are not restriction factors for MmuPV1 infection of murine keratinocytes, at least in vitro, as their loss would otherwise result in higher levels of MmuPV1 transcripts." (PMID 39813296, 2025). "Similarly, infection of Tmc6-/-, Tmc8-/-, and wildtype murine keratinocytes produced similar levels of viral transcripts." (PMID 39813296, 2025). "Likewise, upon percutaneous vaccinia virus challenge, both Tmc6-/- and Tmc8-/- mice controlled infection and induced vaccinia neutralizing antibody titers similarly to wildtype mice." (PMID 39813296, 2025). "We show establishment of MmuPV1 infection is similar to wildtype FVB mice, but thereafter more persistent in Tmc6-/- or Tmc8-/- mice." (PMID 39813296, 2025). "Since wildtype FVB mice better control and clear MmuPV1 infections, we reasoned that adoptive transfer of splenocytes from wildtype FVB mice to MmuPV1-infected Tmc6-/- or Tmc8-/- mice might trigger viral clearance." (PMID 39813296, 2025). "The CD8+ T cells of wildtype, Tmc6-/- or Tmc8-/- mice responded similarly to activation by either stimulus, and these responses were not consistently impacted by MmuPV1 infection." (PMID 39813296, 2025). "Lesions were detectable in the Tmc6-/- and Tmc8-/- mice, but not in the wildtype FVB mice after vaginal challenge as the latter had controlled or eliminated their MmuPV1 infections at the time of sampling." (PMID 39813296, 2025).
cardiovascular disease (1 paper, 2023). "In addition, we identified several interesting candidates such as Taf4b, Tmc8, Wdr11, and Grk5 that were previously associated with different chronic metabolic and inflammatory diseases including T2D, cardiovascular disease, and/or IBD69,70,74,76,77,80,81." (PMID 36788222, 2023).
TMC8 also shares sentences with these, for which no sentence is quoted: skin carcinoma (3 papers); ataxia telangiectasia (1); bacterial infections (1); bare lymphocyte syndrome (1); breast carcinoma (1); Clouston syndrome (1); combined immunodeficiency (1); cutaneous squamous cell carcinoma (1); genetic disorder (1); immunodeficiency (1); leukocyte adhesion deficiency (1); lymphoma (1); Netherton syndrome (1); skin disorder (1); squamous cell carcinoma (1); WHIM syndrome (1).